PROS1 (protein S)
Diseases named in the same sentence as PROS1 in open-access papers (continued):
Sharing a sentence is not in itself a finding about the gene and the disease.
cancer (continued). "In co-culture studies with the breast cancer cell line MDA-MB.231, which expresses high levels of MerTK, we could show that low concentrations of Pros1 resulted in an enhanced inhibition of T cell activation by the cancer cells." (PMID 33801886, 2021). "In the TME, this sets the stage for competition for Pros1 between cancer cells and T cells, and this balance may affect aspects of immune microenvironment resolution." (PMID 33801886, 2021). "Our subsequent qRT-PCR validation in tissue and plasma also revealed low expression of lncRNA RP11-328K4.1 and PROS1 mRNA but high expression of miRNA hsa-miR-27a-3p in cancer tissue and peripheral plasma compared to the levels observed in adjacent normal tissue and healthy human peripheral plasma." (PMID 31956102, 2020). "These novel findings demonstrate that Tyro3 is also linked to cancer cell survival as well as proliferation through the actions of ProS1, given that ProS1 only activates Tyro3 and not Axl." (PMID 31766614, 2019). "Therefore, our data demonstrate that cancer cells can be a major source of functional ProS1, expressed and modified post-translationally in a vitamin K-dependent process exactly as that which exists for several vitamin K-dependent proteins in the liver." (PMID 31766614, 2019). "Moreover, we have identified cancer cells as a source of functional ProS1 as a potential paracrine or autocrine Tyro3 ligand." (PMID 31766614, 2019). "Furthermore, the cancer cell-derived ProS1 was shown to be active due to gamma-carboxylation in a vitamin K-dependent process, as warfarin pre-treatment of producer cells rendered the conditioned medium ineffective on Tyro3 in responder cells." (PMID 31766614, 2019). "Furthermore, cancer cells can secrete a ProS1 molecule that is fully functional due to a local vitamin K-dependent post-translational process." (PMID 31766614, 2019). "Our results point to PROS1 as a potential novel anti-cancer therapeutic target." (PMID 28118606, 2017). "The Gas6/ProS1–TAM interaction is involved in a number of cellular biological processes including regulating the immune system and inflammation, cell survival, migration, proliferation and removal of apoptotic cells, and aberrant TAM signalling has also been implicated in cancers." (PMID 35518197, 2022). "In addition, ProS1 protected cancer cells from acute apoptosis induced by staurosporine, as well as additionally, long-term serum starvation-induced apoptosis in MGH-U3 cells (Tyro3 only), which reflects its additional coupling to Akt signalling in these cells." (PMID 31766614, 2019). "PROS1 is highly expressed in Cancer Cells, Endothelial Cells, Fibroblasts, and M1 Macrophages, and; SCGB2A2 is highly expressed in Cancer Cells, Epithelial Cells, and Granulosa, TRO is expressed in Fibroblasts." (PMID 37985782, 2023). "Alongside wildtype ProS1, only the chimera containing ProS1 LG1 domain stimulated Tyro3 and Erk phosphorylation in human cancer cells, as determined by Western blot." (PMID 35518197, 2022). "Cancer cells that express high levels of TAM receptors, including MerTK, also express the ligands Gas6 and/or Pros1, as well as PtdSer on the outer membrane." (PMID 33801886, 2021). "In the present study, we have demonstrated that Gal-3 is a novel functional agonist for Tyro3 RTK in human cancer cells and have compared it directly against both well-established TAM ligands Gas6 and ProS1." (PMID 32664510, 2020). "This review will focus on PtdSer as a cofactor required for stimulating TYRO3, AXL and MERTK – comprising the TAM family of receptor tyrosine kinases by their ligands Protein S (PROS1) and growth-arrest-specific 6 (GAS6) in inflammation and cancer." (PMID 31775787, 2019). "Under these conditions, both ProS1 and Gas6 significantly protected cells from apoptosis in both SCC-25 (Tyro3 and Axl) and MGH-U3 (Tyro3 only) cancer cell lines." (PMID 31766614, 2019).
cancer (continued). "Our study is the first to detect and evaluate the role of PROS1 in OSCC, and prompts further investigation for the involvement of PROS1 in other cancer models." (PMID 28118606, 2017). "These dynamic insights into the PROS1-MERTK complex, highlighted by significant structural adaptability and the presence of specific binding interfaces, offer promising therapeutic avenues for cancers where MERTK signaling is deregulated." (PMID 39535659, 2025). "Critically, the PROS1-AXL signaling axis is not confined to cancer biology but plays important roles within nervous system and neuroinflammation." (PMID 41383633, 2025). "In conclusion, this study elucidated that PROS1 is upregulated in LGG and various other types of human cancers and may serve as a novel prognostic biomarker in LGG." (PMID 35879775, 2022). "In this study, the upregulated PROS1 was identified in PTC tissues, by integrating bioinformatics methods and in vitro experiments, as the only immune-related hub gene to be deregulated in this type of cancer." (PMID 34414029, 2021). "Compared to normal controls, the expression of PROS1 mRNA was significantly downregulated in ICC patient cancer tissues (p<0.05) but not in peripheral plasma (p>0.05)." (PMID 31956102, 2020). "Exogenous Gal-3 rapidly stimulated Tyro3 receptor phosphorylation to the same extent as the Tyro3 ligand ProS1, but not Axl, in the cultured human cancer cell lines SCC-25 (express both Tyro3 and Axl) and MGH-U3 (express Tyro3 only)." (PMID 32664510, 2020). "In the present study, however, we did not observe Axl nor Akt stimulation by ProS1 in Axl-expressing cancer cells." (PMID 31766614, 2019). "In addition, we were interested to determine the functionality of endogenous ProS1 secreted by human cancer cells, and therefore, its potential as an autocrine or paracrine TAM ligand on cancer cells." (PMID 31766614, 2019). "Since increased APC resistance in cancer has been detected in several previous studies, adjustments were made for the hemostatic parameters that correlated to APC resistance; protein C (ρ = -0.18, P = 0.003), protein S (ρ = -0.33, P < 0.001), and free TFPI (ρ = -0.42, P < 0.001)." (PMID 25407022, 2014). "Second, region-specific ligand–receptor interactions between cancer cells and CAFs—such as ANGPTL4–SDC2, PROS1–AXL, and SEMA4A/D–PLXNB2—have not been systematically validated in large clinical cohorts, and their therapeutic relevance in clinical contexts remains to be determined." (PMID 40723284, 2025).
infection (195 papers, 2008 to 2026). The state of being infected such as from the introduction of a foreign agent such as serum, vaccine, antigenic substance or organism. "The notion that comparing local but not global S protein similarities is crucial in determining SARS-like coronavirus S proteins was therefore consistent with the notion that comparing local but not global ACE2 similarities is crucial in determining mammals at high risk of infection by SARS viruses." (PMID 33462320, 2021). "We then demonstrated that PROS1 concentrations in the media of infected cultures were higher than in the controls, indicating elevated secretions of PROS1 upon infection." (PMID 40980495, 2025). "The study presents evidence that PROS1 release occurs following infection and coincides with a shift from proinflammatory to regenerative epithelial phenotypes." (PMID 40980495, 2025). "In this study, we find that the exogenous administration of PROS1 mitigates lung injury and protects mice from lethal infection by IAVs through the activation of AXL." (PMID 41158072, 2025). "Having shown that PROS1 is secreted upon SARS-CoV-2 infection from the bronchial epithelium and its effects on epithelial cell phenotypes during infection, we further investigated mechanisms that regulate PROS1 secretion." (PMID 40980495, 2025). "The detection of protein C and protein S is easily affected by many factors, such as age, sampling time, medication, infection, and type of gene variation." (PMID 36658687, 2023). "Protein S in serum is also dispensable in AXL-induced SARS-CoV-2 virus pseudotype infection, as evaluated by using serum-free media." (PMID 33420426, 2021). "Of interest, cesarean delivery and infection exacerbate the reduction in free protein S concentrations." (PMID 25426334, 2014). "Protein S activity fluctuated throughout the course of infection, with decreased activity noted beginning at day 3 p.i.." (PMID 22194683, 2011). "Similarly, the mechanisms by which CSFs drove PROS1 upregulation in monocytes and the role of PROS1 in phagocytosis of apoptotic epithelial cells during infection remain to be elucidated in future work." (PMID 40980495, 2025). "To confirm that the loss of PROS1 protein in basal cells during infection was a result of its rapid release rather than inhibition of mRNA expression, we interrogated our transcriptomic data." (PMID 40980495, 2025). "After establishing that PROS1 is secreted from the epithelium upon infection with SARS-CoV-2, limiting inflammation and potentially driving regeneration of damaged epithelium, we sought to understand the mechanism that drives PROS1 expression and production during infection." (PMID 40980495, 2025). "Importantly, we showed that pre-pandemic serum samples contain IgG antibodies reacting to the majority of protein S epitopes, most likely as a result of prior infection with seasonal coronaviruses." (PMID 37251407, 2023). "First, we examined whether the expression of GAS6 and the second TAM ligand, PROS1, in the gingiva is affected by the infection." (PMID 29967614, 2018). "Protein S nadir at delivery and this reduction is exacerbated by cesarean delivery and infection." (PMID 25426334, 2014). "Infection of BHK cells by Sindbis virus (SV) gives rise to a profound inhibition of cellular protein synthesis, whereas translation of viral subgenomic mRNA that encodes viral structural proteins, continues for hours." (PMID 19274090, 2009). "Responsible for structuralconformation of protein S. In other related coronaviruses, NTD facilitatesthe infection by recognizing glycoproteins." (PMID 38687959, 2024). "For example, hAxl was recently shown to enhance the infection mediated by the entry proteins of SINV, RRV and Baculovirus in a PS-dependent manner by binding the serum proteins Gas-6 and Protein S, which in turn bind PS displayed on these viruses' membranes." (PMID 23555248, 2013).
infection (continued). "This similar effect observed in these two clusters between PROS1-stimulated controls and infected ALI cultures could be due to PROS1 secretion by the epithelium during infection." (PMID 40980495, 2025). "To test whether the cellular loss of PROS1 protein is due to its secretion by the basal cells, we evaluated PROS1 concentration in the media of infected and control ALI cultures at 24- and 72-hour post-infection." (PMID 40980495, 2025). "The data showed that infection resulted in increased PROS1 concentration in media from infected cells at both timepoints, explaining the absence of PROS1 detection in the basal cells by immunofluorescence." (PMID 40980495, 2025). "A total of six gibbons were chronic carriers, as defined by the presence of HBV DNA and HBsAg in the absence of antibody to protein S, and the remaining four gibbons showed previous infection." (PMID 25559671, 2015).
blood disorders (8 papers, 2010 to 2025). "Protein S was decreased in SLE patients with active hematologic disease as defined by the BILAG index." (PMID 20637106, 2010). "Levels of free protein S were significantly lower in SLE patients with a history of serositis, neurologic disorder, hematologic disorder and immunologic disorder." (PMID 20637106, 2010). "The concentrations of free protein S were significantly lower in SLE patients with a history of serositis, neurologic disorder, hematologic disorder, and immunologic disorder (defined by meeting 1982 revised ACR criteria than in those patients without these SLE features." (PMID 20637106, 2010).
kidney disease (7 papers, 2014 to 2026). "Of the remaining proteins, which have rarely been reported with regard to their function in renal disease, we conducted validation experiments on two proteins, protein S and galectin-1, to confirm their potential status as candidates in renal pathogenesis." (PMID 33453410, 2021).
neurological disorders (6 papers, 2010 to 2023). "Protein S-palmitoylation is a reversible post-translational lipid modification that plays a critical role in neuronal development and plasticity, while dysregulated S-palmitoylation underlies a number of severe neurological disorders." (PMID 35819139, 2022). "Specifically, C9, FV, PROS1 and C1s were all significantly up-regulated in NT1 patients compared to controls without neurological disorders." (PMID 37122721, 2023).
genetic diseases (5 papers, 2012 to 2024). "PROS1 L607S may be because the mutated residues affect the level of translation and post-translation modification, resulting in disordered protein processing and secretion, which is the main molecular disease mechanism of most missense and other mutations in genetic diseases." (PMID 34496879, 2021).
myopathies (4 papers, 2009 to 2023). "Birds suffering from this myopathy exhibit down-regulation of eight hemostatic genes (A2M, FGA, FGB, FGG, KNG1, SERPINC1 and VWF) and up-regulation of four other coagulation genes (F5, F10, PROS1 and F2R)." (PMID 26445145, 2015).
inflammation (1 paper, 2025). Aberrant reaction of the microcirculation characterized by movement of fluid and leukocytes from the blood into extravascular tissues. "These include the downregulation of natural anticoagulants present on the EC surface (TFPI, TM, and EPCR) mediated by TNF-α and IL-1β, as demonstrated in both acute and chronic inflammation, and variation of protein S and upregulation of endothelial adhesive molecule expression." (PMID 39877523, 2025).
PROS1 also shares sentences with these, for which no sentence is quoted: neurodegenerative disease (23 papers); Alzheimer disease (14); cardiovascular disease (13); ovarian carcinoma (11); bacterial infection (9); cervical cancer (9); dengue (9); Liver fibrosis (8); multiple myeloma (8); neuroblastoma (8); anemia (7); breast tumors (7); cardiomyopathy (7); heart failure (7); type 2 diabetes (7); cyst (6); leukemia (6); metabolic disorders (6); rheumatoid arthritis (6); acute myeloid leukemia (5); cardiac hypertrophy (5); cardiac ischemia (5); depression (5); Disseminated intravascular coagulation (5); HIV-1 infection (5); iron deficiency (5); osteoarthritis (5); osteosarcoma (5); polycythemia vera (5); renal fibrosis (5).
A further 364 diseases each share a sentence with PROS1 in 4 papers or fewer.